IGKV3OR2-268 (immunoglobulin kappa variable 3/OR2-268 (non-functional))
Synonyms: IGKV3/OR2-268; IGKV3/OR2-268A; formerly IGKV268; IGKV3OR2-268A
Gene: Immunoglobulin variable (V) gene on chromosome 2 (87,338,511 to 87,339,035, forward strand). Ensembl gene ENSG00000233999.
Gene Ontology:
Biological process: immune response
Cellular component: immunoglobulin complex; extracellular region; plasma membrane
Homologues: Orthologues: mouse Igkv18-36 (67% identical), rat Igkvl13 (66% identical). Paralogues in human: IGKV3-7 (96% identical), IGKV3D-7 (95% identical), IGKV3-11 (92% identical), IGKV3-15 (92% identical), IGKV3D-11 (91% identical), IGKV3D-15 (91% identical), IGKV3-20 (90% identical), IGKV3D-20 (88% identical), IGKV1-39 (72% identical), IGKV1D-39 (72% identical), IGKV1D-8 (71% identical), IGKV1-6 (70% identical), and 81 more.